SCNN1B (sodium channel epithelial 1 subunit beta)
Description:
This is one of the three pore-forming subunits of the heterotrimeric epithelial sodium channel (ENaC), a critical regulator of sodium balance and fluid homeostasis. ENaC operates in epithelial tissues, where it mediates the electrodiffusion of sodium ions from extracellular fluid through the apical membrane of cells, with water following osmotically. It plays a key role in maintaining sodium homeostasis through electrogenic sodium reabsorption in the kidneys. Additionally, ENaC is essential for airway surface liquid homeostasis, which is crucial for proper mucus clearance.
Synonyms: Beta-ENaC; ENaCB; ENaCbeta; BESC1; LIDLS1; PHA1B2; SCNEB; beta-NaCH
Tractability: Small molecule: an approved drug acts on it; it belongs to a druggable protein family. Antibody: UniProt places it where antibodies can reach, with high confidence; its Gene Ontology location is reachable by antibodies, with high confidence; UniProt predicts a signal peptide or a membrane-spanning region. PROTAC: UniProt records ubiquitination sites on it; ubiquitination databases record sites on it.
Target class: Ion channel; Ligand-gated ion channel; Epithelial sodium channel
Chemical probes: BI-8668 (high quality)
Safety:
Unwanted effects reported when the protein is acted on. In parentheses: how it was acted on, where the effect was seen, and who reports it.
oedema (source: ClinPGx)
Gene: Protein-coding gene on chromosome 16 (23,278,231 to 23,381,299, forward strand). Ensembl gene ENSG00000168447.
Subcellular location: Apical cell membrane; Cytoplasmic vesicle membrane
Pathways (Reactome):
Sensory Perception: Sensory perception of salty taste
Transport of small molecules: Stimuli-sensing channels
Gene Ontology:
Molecular function: protein binding; sodium channel activity; WW domain binding; ligand-gated sodium channel activity; sodium ion transmembrane transporter activity
Biological process: cellular response to acidic pH; intracellular sodium ion homeostasis; multicellular organismal-level water homeostasis; sodium ion homeostasis; sodium ion import across plasma membrane; sodium ion transmembrane transport; cellular response to aldosterone; cellular response to vasopressin; regulation of blood pressure; sensory perception of salty taste; sensory perception of sour taste; sodium ion transport
Cellular component: apical plasma membrane; extracellular exosome; plasma membrane; sodium channel complex; cytoplasmic vesicle membrane; apical part of cell; external side of plasma membrane; membrane
Genetic constraint (gnomAD): Loss-of-function variants: 45 observed, 71.26 expected, observed/expected ratio (o/e) 0.63, 90% interval 0.5 to 0.81. The upper end of that interval is the gene's LOEUF score, 0.81, which puts it in group 3 of 6, group 1 being the genes least tolerant of losing a copy. Missense variants: 742 observed, 864.48 expected, observed/expected ratio (o/e) 0.86, 90% interval 0.81 to 0.91. Synonymous variants: 349 observed, 347.97 expected, observed/expected ratio (o/e) 1, 90% interval 0.92 to 1.1.
Homologues: Orthologues: chimpanzee SCNN1B (99% identical), dog SCNN1B (88% identical), pig SCNN1B (85% identical), rat Scnn1b (84% identical), mouse Scnn1b (84% identical), rabbit SCNN1B (83% identical), guinea pig SCNN1B (82% identical), macaque SCNN1B (81% identical), tropical clawed frog scnn1b (60% identical), Caenorhabditis elegans mec-10 (22% identical), Caenorhabditis elegans mec-4 (22% identical), Caenorhabditis elegans acd-2 (20% identical), and 21 more. Paralogues in human: SCNN1G (37% identical), SCNN1A (30% identical), SCNN1D (25% identical), ASIC1 (20% identical), ASIC2 (19% identical), ASIC4 (19% identical), ASIC5 (19% identical), ASIC3 (18% identical).
Diseases named in the same sentence as SCNN1B in open-access papers:
SCNN1B is named in the same sentence as 55 diseases in open-access papers, as found by Europe PMC text mining. Sharing a sentence is not in itself a finding about the gene and the disease. The quoted sentences say what the papers report.
lung disease (15 papers, 2008 to 2025). "In contrast, an increased expression of Scnn1b in mice causes CF-like lung disease." (PMID 34680949, 2021). "Therefore, we hypothesized that airway epithelial cell-specific deficiency of EGFR mitigates mucoinflammatory responses in Scnn1b-transgenic (Tg+) mice that phenocopy human CF-like lung disease." (PMID 40406132, 2025). "In the current study, the O3 exposure of Scnn1b-Tg+ lung disease resulted in alveolar space enlargement, which is likely an outcome of enhanced macrophage and neutrophil recruitment, and an increase in MMP12-expressing macrophages." (PMID 40496925, 2025). "Accordingly, we investigated the role of airway epithelial cell-specific EGFR in the pathogenesis of mucoinflammatory lung disease in Scnn1b-transgenic (Scnn1b-Tg+) mice, a mouse model of human CF-like lung disease." (PMID 40406132, 2025). "To increase the safety profile of mucosal BCG vaccination, we studied BCG with a “kill switch” (tetR BCG) in scnn1b-transgenic mice (i.e., mice prone to cystic fibrosis-type lung diseases)." (PMID 40573950, 2025). "In this study, we investigated the role of airway epithelial cell-specific EGFR signaling in the pathogenesis of mucoinflammatory lung disease in Scnn1b-transgenic (Tg+) mice, a mouse model of human CF-like lung disease." (PMID 40406132, 2025). "The Scnn1b-Tg+ (Tg+) mouse, a model of human CF-like lung disease, also exhibits elevated levels of HMGB1 in BALF." (PMID 36741411, 2022). "Accordingly, we investigated the role of airway epithelial cell-derived HMGB1 in the pathogenesis of muco-obstructive lung disease in Scnn1b-transgenic (Scnn1b-Tg+) mouse, a model of human CF-like lung disease." (PMID 36741411, 2022). "Here, we investigated the role of airway epithelium-specific HMGB1 in the pathogenesis of muco-obstructive lung disease in Scnn1b-transgenic (Tg+) mouse, a model of human cystic fibrosis -like lung disease." (PMID 36741411, 2022). "Over-expression of ENaC channels in SCNN1B transgenic mice has been used as a model of CF lung disease, and suppression of ENaC subunit expression is being explored as therapeutic strategies." (PMID 33253230, 2020). "Selective introduction of additional genetic alterations into the Scnn1b-Tg+ strain have already begun to dissect the pathway-specific roles of various genes in the pathogenesis of mucoobstructive lung disease." (PMID 31396541, 2019). "In Section 4.5, we will review the characteristics of this strain and modulation of Scnn1b-Tg+ lung disease upon various other genetic alterations." (PMID 31396541, 2019). "Taken together, these mechanistic reports that focused on the numerical depletion of macrophages highlighted the critical roles of these cells in the pathogenesis of lung disease in Scnn1b-Tg+ mice." (PMID 31396541, 2019). "The robust molecular signatures exhibited by pulmonary macrophages during the progression of mucoobstructive lung disease in Scnn1b-Tg+ mice indicated their critical role in disease pathogenesis." (PMID 31396541, 2019). "The gene expression analyses reported here provide a global appreciation for the complexity of the development of lung disease in the Scnn1b-Tg model." (PMID 25204199, 2014). "To identify the bronchoalveolar lavage fluid (BALF) exosome-bound proteins associated with mucoinflammatory lung disease and to gain insights into their functional implications, we compared BALF exosomes-derived proteins from adult Scnn1b transgenic (Scnn1b-Tg+) and wild type (WT) mice." (PMID 39386033, 2024). "The Scnn1b-Tg+ mouse also presents an outstanding tool to investigate the impact of various environmental insults, e.g., cigarette smoke, nanoparticles, and fungal spores, on the development and progression of mucoobstructive lung disease." (PMID 31396541, 2019). "The role of ILCs in the pathogenesis and progression of lung disease in the Scnn1b-Tg+ mouse model remains unclear and warrants extensive investigation." (PMID 31396541, 2019).
lung disease (continued). "The Scnn1b-Tg+ (Tg+) mice, due to ion channel dysfunction-mediated ASL dehydration, manifest most of the CF lung disease features." (PMID 40496925, 2025). "On the opposite, the Scnn1b transgenic model presents a CF-like lung disease but has no intestinal defect." (PMID 35721541, 2022). "Although not modulating the functioning of CFTR channels, the Scnn1b-Tg+ mouse model effectively demonstrates how a single ion-channel defect results in an imbalance in ion transport, which ultimately leads to ASL dehydration and associated lung disease." (PMID 31396541, 2019). "However, the exact role of eosinophils in Scnn1b-Tg+ lung disease is not yet clear." (PMID 31396541, 2019).
Hypertension (13 papers, 2009 to 2025). The presence of chronic increased pressure in the systemic arterial system. "The SCNN1B gene revealed 3 nonsynonymous variants (R206Q, G442V, and R563Q), 2 of which were previously known, with one associated with hypertension." (PMID 40536937, 2025). "In contrast, people with homozygous TT of SCNN1B, rs239345 had approximately 45% decreased risk of hypertension compared to carriers of the A allele." (PMID 34150338, 2021). "Risk for hypertension was observed in two polymorphisms, specifically SCNN1B, rs239345, and TRPV1, rs8065080." (PMID 34150338, 2021). "In contrast, people with homozygous TT of SCNN1B, rs239345 were 45% less likely to have hypertension compared to carriers of the A allele." (PMID 34150338, 2021). "Liddle syndrome is an autosomal dominant genetic condition that causes hypertension and hypokalemia due to a gain-of-function mutation in the SCNN1B or SCNN1G genes which code for the epithelial sodium channel in the kidney." (PMID 28396810, 2017). "Mutations of the PPxY-motif in SCNN1B are linked to Liddle syndrome 1, a hereditary form of hypertension caused by augmented Na2+ transport, and result in the loss of interaction with the HECT type E3 ligases and increased stability of the transmembrane protein." (PMID 39009827, 2024). "In addition, risk for hypertension was observed between the TT genotype and carriers of the A allele (AT and AA) in SNP rs239345, SCNN1B gene with odds ratio 0.55 (P=0.024) and a 95% confidence interval of 0.34–0.91." (PMID 34150338, 2021). "Moreover, the polymorphism of TRPV1, rs8065080, and SCNN1B, rs239345, genes were associated with a risk of hypertension (P=0.016 and P=0.024)." (PMID 34150338, 2021). "We have previously shown a relationship of the R563Q mutation of the SCNN1b gene with hypertension, but the prevalence of this SNP in the hypertensive population is 5% and <1% in normotensives and cannot account for the suppressed plasma renin activity in 70% of indigenous Africans." (PMID 20886000, 2010). "Moreover, the p.T594M but not p.G442V (which causes lower aldosterone secretion, suggesting increased ENaC activity) variants in SCNN1B may also contribute to hypertension in African Americans." (PMID 30832344, 2019). "Constitutive activation variants of SCNN1B or SCNN1G result in salt-sensitive hypertension known as Liddle’s syndrome, an autosomal dominant form of monogenic hypertension that is characterized by early-onset of low-renin hypertension." (PMID 30832344, 2019). "The hypermethylation of ACE II, SCNN1B, CKG, IFN-γ gene, and miR-510 promoter were associated with hypertension, the common effect size (CES) = 6.0%, 95% CI, −0.002–11.26." (PMID 31805646, 2019). "Liddle syndrome is genetic autosomal dominant form of low renin arterial hypertension caused by germline mutations in the SCNN1A, SCNN1B and SCNN1G genes, encoding, respectively, the α, β and γ subunits of the epithelial sodium channel ENaC." (PMID 29534496, 2018). "Activation of ENaC, either due to structural variants of the channel subunits (e.g.,: SCNN1B) or altered activity of regulatory processes (including NEED4), could underlie low-renin hypertension in African Americans." (PMID 30832344, 2019). "Despite our previous description of the association of hypertension with the R563Q mutation, the SCNN1b gene was not identified as a good candidate gene." (PMID 20886000, 2010).
Liddle syndrome (11 papers, 2017 to 2024). A rare genetic form of low-renin hypertension characterized by hypertension associated with decreased plasma levels of potassium and aldosterone. "In this study, we report a novel frame-shift mutation in SCNN1B responsible for Liddle syndrome in a Chinese family." (PMID 35774371, 2022). "We identified a novel frame-shift mutation (c.1691_1693delinsG) in SCNN1B that was responsible for Liddle syndrome in this family." (PMID 35774371, 2022). "In the present study, we report a Chinese family with Liddle syndrome and identify a novel frame-shift mutation (c.1691_1693delinsG) in SCNN1B by whole-exome sequencing." (PMID 35774371, 2022). "Scnn1b was considered to be one of the candidate genes to influence kidney function because mutations of Scnn1b are a cause of Liddle’s syndrome, which results in increased sodium and water reabsorption in the distal nephron." (PMID 29211750, 2017). "Genetic analysis revealed that Liddle syndrome was due to mutations in ENaC subunits, mainly ENaCβ and γ (SCNN1B and SCNN1G genes), leading to the modifications (generally truncation) of a prolin‐rich sequence called PY motif, in the C‐terminal part of the protein." (PMID 35909256, 2023). "Multiple variants in the SCNN1B gene have been reported, many causing complete Liddle’s syndrome." (PMID 29144530, 2017). "Liddle syndrome is associated with germline mutations in an allele of SCNN1A, SCNN1B or SCNN1G genes." (PMID 31655555, 2019). "The cause of Liddle syndrome is missense or frameshift mutations in SCNN1A, SCNN1B, or SCNN1G genes that encode epithelial sodium channel subunits." (PMID 31655555, 2019). "The molecular basis of Liddle syndrome resides in germline mutations of the SCNN1A, SCNN1B and SCNN1G genes, encoding the α, β, and γ-subunits of the epithelial Na+ channel (ENaC), respectively." (PMID 29534496, 2018). "Liddle syndrome results from germline mutations in SCNN1A, SCNN1B or SCNN1G genes." (PMID 29534496, 2018). "Furthermore, some genes may be completely lacking in the zebrafish, such as the ENaC (epithelial Na channel) subunits (SCNN1A, SCNN1B, SCNN1G, and SCNN1D), mutations in which cause Liddle syndrome and pseudohypoaldosteronism type 1 in humans." (PMID 30200518, 2018). "The diagnosis of Liddle syndrome is based on SCNN1A, SCNN1B and SCNN1G gene sequencing." (PMID 29534496, 2018).
cystic fibrosis (8 papers, 2008 to 2025). Autosomal recessive disorder caused by pathogenic variants in the CFTR gene (cystic fibrosis transmembrane conductance regulator), which encodes a chloride and bicarbonate channel expressed in epithelial cells, and follow the diagnosis criteria. "Previously, we reported an association between SNP markers of SCNN1B gene and disease severity in cystic fibrosis-affected sibling pairs." (PMID 33384439, 2020). "In Scnn1b-Tg mice, which overexpress the epithelial sodium channel (ENaC) and exhibit cystic fibrosis-like mucus obstruction and inflammation, Siglec-F+ neutrophils were present at baseline in bronchoalveolar lavage and were further recruited during chronic Pseudomonas aeruginosa infection." (PMID 41301697, 2025). "In adult conditional Nedd4-2−/− mice, we demonstrated that increased ENaC-mediated Na+/fluid absorption across airway epithelia, as previously shown in patients with cystic fibrosis and Scnn1b-Tg mice, results in airway surface liquid depletion and impaired mucociliary clearance." (PMID 34200296, 2021). "In this review, we will focus our discussion on MCC defect in cystic fibrosis and its recapitulation in a widely accepted mouse model of CF, i.e., Scnn1b-Tg+ mouse." (PMID 31396541, 2019).
gastric cancer (8 papers, 2022 to 2025). A primary or metastatic malignant neoplasm involving the stomach. "By promoting the ubiquitination and degradation of GRP78, SCNN1B prevents the growth and metastatic spread of stomach cancer." (PMID 39267084, 2024). "SCNN1B is a methylation-related suppressor gene mentioned in renal cell carcinoma and gastric cancer." (PMID 39415304, 2024). "The methylation levels of SCNN1B gene promoter regions were significantly increased in gastric cancer and renal cell carcinoma." (PMID 39415304, 2024). "It was confirmed that ADH7, CWH43 and SCNN1B all showed low expression in gastric cancer cells (p < 0.05)." (PMID 37359529, 2023). "In this study, three biomarkers, ADH7, CWH43 and SCNN1B, were included in the model that used multiple bioinformatics methods to screen for gastric cancer." (PMID 37359529, 2023). "Our previous work has shown that SCNN1B suppresses gastric cancer, but the functional importance and molecular mechanism of SCNN1B in CRC is largely unclear." (PMID 36564468, 2023). "SCNN1B (sodium channel epithelial 1 subunit beta), a methylation-related differentially expressed gene was mentioned in gastric cancer and renal cell carcinoma (RCC)." (PMID 35093172, 2022). "Hypermethylation of SCNN1B was identified as an prognostic factor in gastric cancer patients." (PMID 39415304, 2024). "Moreover, hypermethylation of SCNN1B was a prognostic factor that predicts worse survival in patients with gastric cancer." (PMID 39415304, 2024). "Elevated SCNN1B expression serves as an independent prognostic marker for prolonged survival in patients with advanced gastric cancer (GC)." (PMID 39744692, 2025). "SCNN1B interacted with GRP78 and induced its degradation, which led to Caspase-dependent apoptosis and ultimately inhibited cell growth and migration in gastric cancer." (PMID 37334354, 2023).
bronchiectasis (5 papers, 2008 to 2023). Segmental, irreversible dilation of the bronchial tree resulting in the accumulation of secretions which leads to obstruction. "The variants involved two genes associated with surfactant metabolism dysfunction (ABCA3 and CSF2RB), two with pulmonary fibrosis (MUC5B and SFTP), one with bronchiectasis (SCNN1B), and one with alpha-1-antitrypsin deficiency (SERPINA1)." (PMID 33526882, 2021). "Bronchiectasis with or without elevated sweat chloride-1 (BESC1 OMIM:211400) is caused by heterozygous mutation in the gene encoding the β-subunit of ENaC (SCNN1B)." (PMID 37175488, 2023). "In addition, SAE ionocytes also expressed the high levels of epithelial Na+ channel genes (SCNN1A, SCNN1B, SCNN1G), risk genes relevant to CF and bronchiectasis." (PMID 32727470, 2020).
colorectal cancer (5 papers, 2020 to 2024). A primary or metastatic malignant neoplasm that affects the colon or rectum. "Ectopic expression of SCNN1B in colorectal cancer cell lines resulted in the suppression of cell proliferation, induced apoptosis and cell cycle arrest, and suppressed cell migration." (PMID 38681779, 2023). "Moreover, using Gene Expression Omnibus (GEO) datasets, SCNN1B expression was significantly decreased in cervical cancer, lung squamous cell carcinoma and colorectal cancer." (PMID 39415304, 2024). "Furthermore, SCNN1B could inhibit the growth of colorectal cancer by impairing the activation of c-Raf and suppressing MAPK signaling." (PMID 37334354, 2023). "SCNN1B and DDX27 are significantly related to colorectal cancer." (PMID 32854705, 2020).